SKP1 (S-phase kinase associated protein 1)
Diseases named in the same sentence as SKP1 in open-access papers (continued):
Sharing a sentence is not in itself a finding about the gene and the disease.
Obesity (2 papers, 2021 to 2025). Accumulation of substantial excess body fat. "Moreover, CUL1 (along with SKP1 (S-phase-kinase-associated protein 1) and F-Box protein) forms the largest E3 ubiquitin ligase family (Skp1-Cullin1-F-box (SCF)) E3 ligase is known for controlling obesity with an association of Skp2." (PMID 33669862, 2021).
prostate carcinoma (2 papers, 2017 to 2025). A carcinoma that arises from epithelial cells of the prostate gland. "We analyzed expressions of known p27-targeting E3 ubiquitin ligases, such as CUL1 (cullin 1), SKP1 (S-phase kinase associated-protein 1), and SKP2, in prostate cancer cells." (PMID 40251202, 2025). "Some prostate cancer cells even develop an androgen-repressed phenotype and cell culture and xenograft studies indicate that androgen treatment inhibits cancer cell proliferation via Skp1, c-Myc and p27 in this setting." (PMID 29108248, 2017).
pulmonary fibrosis (2 papers, 2018 to 2023). Chronic progressive interstitial lung disorder characterized by the replacement of the lung tissue by connective tissue, leading to progressive dyspnea, respiratory failure, or right heart failure. "Compared with the control group, the BLM-induced pulmonary fibrosis group exhibited significantly higher expression of Fmod and Tgfbr2 mRNA; in contrast, the mRNA expression levels of Bambi, Skp1, Zfyve9, Zfyve16, Ppp2ca, Ppp2r1a, Ppp2r1b, Rps6kb1, and Rps6kb2 were markedly lower." (PMID 38259493, 2023). "Alternatively, if combined inhibition of the degradation of several Skp2 targets is required, inhibitors of the Skp1/Skp2 interaction or inhibitors of Skp2 expression may be effective against pulmonary fibrosis." (PMID 29415439, 2018). "In contrast to the control mice, mice with pulmonary fibrosis exhibited notably higher levels of lung proteins such as TGF-βR2, SKP-1, CHI3L1, OGG1, and Galectin-3, alongside lower expression of p-4Ebp1, SARA, p-P70S6K, and PP2A." (PMID 38259493, 2023).
serous ovarian cancer (2 papers, 2021 to 2022). "On the other hand, it was suggested that SKP1 could have an anti-tumor effect in high-grade serous ovarian cancer (HGSOC)." (PMID 35565454, 2022).
3-M syndrome (1 paper, 2015). 3M syndrome is a primordial growth disorder characterized by low birth weight, reduced birth length, severe postnatal growth restriction, a spectrum of minor anomalies (including facial dysmorphism) and normal intelligence. "An intriguing recent finding is that Cul7-Fbw8 can degrade the insulin receptor substrate 1 (IRS-1) through Skp1-Fbw8-ROC1 (SCF complex), suggesting the mechanism of 3-M syndrome is related to IRS-123." (PMID 26423533, 2015).
cardiac hypertrophy (1 paper, 2024). "Whereas Skp1 has been related to cardiac hypertrophy and the degradation of key sarcomeric proteins, NDUFA4 has been associated with cardiomyocyte apoptosis and mitochondrial dysfunction, two ACM-related processes." (PMID 39200271, 2024).
COVID-19 (1 paper, 2020). A disease caused by infection with severe acute respiratory syndrome coronavirus 2. "Among our results, several immune-related pathways including those activated by Fc-epsilon-related signaling (LYN and PI3K), NIK/NF-κB (ub, CUL1, SKP1, proteasome, and NFKB2), and via C-type lectin receptor pathways (PTPN11 and CARD9) were enriched in the COVID-19 lungs." (PMID 33060566, 2020).
cyst (1 paper, 2012). A sac-like closed membranous structure that may be empty or contain fluid or amorphous material. "The opposing effects of Skp1 overexpression and blocking its modification suggests that modification stimulates Skp1 activity, which can be modeled as breakdown (by a specific E3SCFubiqutin ligase) of a hypothetical activator of cyst formation." (PMID 23098648, 2012). "Formation of the novel cyst-like structures is compared to normal development at an air-water interface as a backdrop to interpreting the role of Skp1 modification in O2 signaling." (PMID 23098648, 2012). "Under these conditions, we find that O2 is apparently rate-limiting for Skp1 hydroxylation, and that cyst formation and terminal spore differentiation that require high O2 also depend on normal levels of Skp1 and both its hydroxylation and glycosylation." (PMID 23098648, 2012). "In comparison, the effect of Skp1 modification on culmination implied inhibition of Skp1 breakdown activity toward a hypothetical activator, and the effects on cyst formation (assessed morphologically) above suggested activation of breakdown activity toward an activator." (PMID 23098648, 2012). "The opposing effects of Skp1 overexpression and inhibiting its modification are consistent with a model in which modification activates Skp1 and its role in polyubiquitination and breakdown of a hypothetical activator of cyst formation." (PMID 23098648, 2012). "Genetic perturbations indicate the importance of Skp1 hydroxylation and glycosylation for activating Skp1 activity in regulating cyst formation and sporulation, in addition to previous evidence for its inhibition in regulating culmination at an air-water interface." (PMID 23098648, 2012). "However, overexpressing mutant Skp1A3(P143A), which cannot be modified, did not interfere with aggregation, and wild-type Skp1 overexpression failed to inhibit cyst formation in the absence of PhyA." (PMID 23098648, 2012).
depression (1 paper, 2023). "The findings revealed that, even after factoring in depression, the previously established associations for HSPA8 and SKP1 remained statistically significant." (PMID 38115821, 2023).
Ewing sarcoma (1 paper, 2013). A small round cell tumor that lacks morphologic, immunohistochemical, and electron microscopic evidence of neuroectodermal differentiation. "Among these, several necessary connections between ubiquitin proteasome system members (CUL1, SKP1, SKP2, ANAPC2) and EWS-FLI1 were identified, potentially indicating an interesting link between this oncogene and the protein turnover regulation in the context of Ewing sarcoma." (PMID 23935076, 2013).
Hypertension (1 paper, 2012). The presence of chronic increased pressure in the systemic arterial system. "We found that the meiotic bent spindle in skp1 cells was due to a hypertension generated by chromosome entanglement." (PMID 22292001, 2012).
inflammatory bowel disease (1 paper, 2023). A spectrum of small and large bowel inflammatory diseases of unknown etiology. "Previous studies suggested that the F-box and WD repeat domain-containing 7 (FBW7), as a substrate receptor (SR) of SKP1–Cul1–F-box (SCF), was predominantly upregulated in the colon tissues of patients with inflammatory bowel disease (IBD) and was correlated with its severity." (PMID 37006236, 2023).
lymphoma (1 paper, 2021). A malignant (clonal) proliferation of B- lymphocytes or T- lymphocytes which involves the lymph nodes, bone marrow and/or extranodal sites. "When FLAG-tagged FBXO10 was expressed in HEK293T cells, the E54K substitution decreased immunoprecipitation of endogenous SKP1 to a similar extent as the partial loss-of-function R44H FBOX mutation previously characterised in a human lymphoma." (PMID 33914737, 2021).
malaria (1 paper, 2024). Malaria is a serious and sometimes fatal disease caused by a parasite that commonly infects a certain type of mosquito which feeds on humans. "To investigate the CRLs of human malaria parasite Plasmodium falciparum, we generated parasites expressing tagged P. falciparum cullin-1 (PfCullin-1), cullin-2 (PfCullin-2), Rbx1 (PfRbx1) and Skp1 (PfSkp1)." (PMID 38416790, 2024). "al. in a recent study performed extensive immunoprecipitation of Rbx1, Skp1 and FBXO1 of the mouse malaria parasite P. berghei, and proposed that these proteins form an SCF in P. berghei." (PMID 38416790, 2024).
male infertility (1 paper, 2023). The inability of the male to effect fertilization of an ovum after a specified period of unprotected intercourse. "Research in wheat (Triticum aestivum) has revealed that reductions in the level of SKP1 affect the growth and development of pollen grains, leading to premature death and male infertility." (PMID 37047551, 2023).
melanoma (1 paper, 2019). A malignant, usually aggressive tumor composed of atypical, neoplastic melanocytes. "With regard to the genes specifically up-regulated in the MCSP CTC fraction, the majority have been involved in metastasis (LOXL4, ST6GALNAC2, PYGL), tumour growth (PLK2, CYSTM1, GLUL), and/or melanoma biology (SEC31A, WIPI1, SKP1)." (PMID 30769764, 2019).
multiple sclerosis (1 paper, 2024). A progressive autoimmune disorder affecting the central nervous system resulting in demyelination. "This study identified IREB2, LAMP2, ISCU, ATP6V1G1, ATP13A2, and SKP1 as genes associated with multiple sclerosis (MS) and iron metabolism, establishing their multi-gene diagnostic value for MS with an AUC of 0.83." (PMID 38590521, 2024).
ovarian tumors (1 paper, 2014). "To assess the possibility that alteration to these components may be contributing to NRF2 activation in ovarian tumors, we evaluated DNA-level alterations affecting the genes involved in this BTRC/SKP1/CUL1 complex." (PMID 25114896, 2014).
renal cell carcinoma (1 paper, 2019). "CUL1 is a scaffold protein of the ubiquitin E3 ligase Skp1/Cullin1/Rbx1/F-box protein complex, which increased in renal cell carcinoma and promotes cancer cell proliferation, migration, and invasion." (PMID 31086232, 2019).
schizophrenia (1 paper, 2016). A major psychotic disorder characterized by abnormalities in the perception or expression of reality. "To address this issue we measured levels of mRNA for six potential reference genes (GAPDH, PPIA, SNCA, NOL9, TFB1M and SKP1) in three cortical regions (Brodmann’s areas (BA) 8, 9 and 44) from 30 subjects with schizophrenia and 30 age and sex matched controls." (PMID 27206773, 2016).
T-cell lymphomas (1 paper, 2022). "Following the initial proliferation reduction, >80% of Cul1-N252 mice develop T-cell lymphomas, suggesting Skp1 and SCF function are required to prevent lymphoid tumor development." (PMID 35345853, 2022). "Interestingly, the in vivo inhibition of Skp1 function in a T-cell lineage corresponded with the development of T-cell lymphomas." (PMID 35345853, 2022).
uterine cancer (1 paper, 2021). Primary or metastatic malignant neoplasm involving the uterine corpus and/or the cervix. "Overall, the methylation status of CUL1 is very similar to that of SKP1, as tumor samples with copy number losses also tend to be hypermethylated; however, CUL1 is generally partially methylated or hypermethylated in all uterine cancer cases." (PMID 35008511, 2021).
tumor (45 papers, 2012 to 2025). "Skp1 overexpression promotes tumor growth, whereas reduced Skp1 activity is also linked with genomic instability and neoplastic transformation." (PMID 35789855, 2022). "FBXW7 is a tumor suppressor gene that encodes the substrate recognition component of SKP1–Cullin1–F-box protein ubiquitin E3 ligase complexes, which in turn negatively regulate the intracellular abundance of several key oncogenic proteins." (PMID 31226844, 2019). "FBXW7 is a tumor-suppressor gene located on human chromosome 4q that encodes a substrate-recognition component of SKP1–Cullin1–F-box protein-ubiquitin E3 ligase complexes." (PMID 30458818, 2018). "CLINK interacts with SKP1 through its F-box motif and associate with the retinoblastoma tumor-suppress protein pRB via an LxCxE motif." (PMID 24176102, 2013). "Interestingly, and in agreement with SKP1 being a putative tumor suppressor gene, the mutational load is equally distributed (i.e., diffuse) across the entire coding sequence, rather than a focal mutational load that is typical of an oncogene." (PMID 35345853, 2022). "The evolutionarily conserved protein FBXO9 acts as a substrate receptor for the SKP1-cullin-1-RBX1 ubiquitin ligase and is implicated in cancer, exhibiting either tumor-suppressive or oncogenic effects depending on the specific tumor type." (PMID 38486234, 2024). "The results demonstrated that SKP1 was highly expressed in tumour tissues, whereas Smad2 and BMPR2 were inhibited, which was consistent with the findings of scRNA‐seq data." (PMID 39548559, 2024). "FBXW7 (also known as CDC4) is a component of the S-phase kinase-associated protein 1 (SKP1)/CUL1/F-box (SCF) E3 ubiquitin ligase complex, which functions as a tumor suppressor which is frequently altered in cancer." (PMID 36694209, 2023). "SKP2 recognized tumor suppressor substrates and was targeted for ubiquitination and degradation by the proteasome via the E3 ligase SKP1-Cullin1-F-box." (PMID 37915040, 2023). "IHC assays showed that upregulation of CCDC183-AS1 enhanced the expression of SKP1 in xenograft tumor tissues." (PMID 33541391, 2021). "F-box only proteins (FBXO) are the core components of SKP1-cullin 1-F-box E3 ubiquitin ligase, which have been reported to play crucial roles in tumor initiation and progression via ubiquitination-mediated proteasomal degradation." (PMID 35046938, 2021). "In agreement with the most prevalent copy number alterations detailed above, SKP1 mRNA expression levels are often reduced within tumor samples relative to normal tissues, whereas CUL1 expression is frequently increased." (PMID 34445249, 2021). "Results showed that SKP1 expression was markedly increased in HCC tissues compared with that in adjacent non-tumor tissues." (PMID 33541391, 2021). "We also found strong nuclear positivity of RBPJ and SKP1 in tumor tissue compared with paratumor tissue, with significant differences (P < 0.05)." (PMID 33329729, 2020). "Cytoplasmic expression of SKP1 was found to be significantly associated with stratifin (SFN) positivity, tumor malignancy, and unfavorable patient outcomes." (PMID 33329729, 2020). "The Fbxo4 tumour suppressor is a component of an Skp1-Cul1-F-box E3 ligase for which two substrates are known." (PMID 29142209, 2017). "FBXW7, an E3-ubiquitin protein ligase in SCFs (SKP1-cullin-F-box) complex, is a major human tumor suppressor gene, and understanding mechanisms by which FBXW7 contributes to tumorigenesis is critical for the treatment of human cancers with FBXW7 deficiency." (PMID 27376155, 2016). "We tested the expression of Skp1 in 64 previously untreated NSCLCs by Western blot and immunohistochemistry, and showed that in 36 (56.3%) of the patients the expression of Skp1 was significantly higher in tumor samples than their adjacent normal lung tissues." (PMID 26474281, 2015). "The densitometry analyses of the Western blot bands and the immunoreactivity score of immunohistochemistry confirmed the elevation of Skp1 in tumor samples." (PMID 26474281, 2015).
tumor (continued). "FBXW7, a component of the SCF (Skp1/Cullin/F-box protein) E3 ubiquitin ligase complex, acts as a tumor suppressor in several tissues and targets multiple transcriptional activators and proto-oncogenes for ubiquitin-mediated degradation." (PMID 22879877, 2012). "F-box and WD repeat domain-containing protein 2 (FBXW2), a substrate receptor of the SKP1-Cullin 1-F-box (SCF) E3 ubiquitin ligase complex, has been implicated in tumor suppression across multiple malignancies; however, its role in GC progression remains undefined." (PMID 40721413, 2025). "In short, the enigmatic interplay of these conjoined yet opposed effects raises the possibility that molecular axes of Skp1 partnership in the cellular machinery could fine-tune and maintain cellular homeostasis of tumor suppressor/promoter proteins." (PMID 35789855, 2022). "Finally, a negative correlation between CCDC183-AS1 and miR-589-5p expression and a positive correlation between CCDC183-AS1 and SKP1 expression were observed in xenograft tumor and HCC tissues." (PMID 33541391, 2021). "Collectively, these findings support the possibility that SKP1, CUL1, and RBX1 encode tumor suppressor- or oncogene-like activities depending on whether they are under- or over-expressed." (PMID 34445249, 2021). "We next examined the association between SKP1 and CRC-SCs markers in tumor samples." (PMID 33292299, 2020). "Interestingly, TCGA data analysis revealed that the CDK1, CDK2, CCNB2, and SKP2 genes were significantly upregulated, but the SKP1 gene was downregulated in tumor samples compared with normal samples." (PMID 31717435, 2019). "Similarly, Fbw7, a well-characterized major tumor suppressor, is the substrate recognition component of the Skp1-Cullin-F-box (SCF)-type E3 ligase complex, which is frequently inactivated by mutation or genetic deletion in various types of human cancer." (PMID 23708493, 2013). "Moreover, we have presented different lines of evidence suggesting that Z0933M recapitulated previously reported effects of Skp1 knockdown and/or Skp1 pharmacological inhibition, such as tumor cell growth inhibition, cell-cycle arrest, and accumulation of proteins associated with replication stress." (PMID 35789855, 2022). "The S-phase kinase-associated protein 1 (SKP1)-cullin-1 (CUL1)-F-box-protein (SCF) complex belongs to the really interesting new gene (RING) family of E3 ubiquitin ligases, mediating the degradation of ~20% proteins related to cell-cycle regulation, transcription, oncogenesis, and tumor suppression." (PMID 35515121, 2022). "PPI analysis indicated that the levels of the mRNAs encoding RBPJ, SKP1, CTNNB1, CDH2, SCG2, VGF, and TFF3 were significantly increased in PanNEN tumor tissues compared with the matched paratumor tissues and may be involved in the DNER signaling pathway in PanNENs." (PMID 33329729, 2020). "Specifically, the F-box protein (FBP), an integral component of the SKP1-Cullin1-F-box protein (SCF) E3 ligase complex within the UPS, has garnered attention for its prominent role in carcinogenesis, tumor progression, and drug resistance." (PMID 38903918, 2024). "F-box and leucine-rich repeat protein 7 (FBXL7), an F-box protein responsible for substrate recognition by the SKP1-Cullin-1-F-box (SCF) ubiquitin ligases, plays an emerging role in the regulation of tumorigenesis and tumor progression." (PMID 35906197, 2022). "DNER regulates its downstream target RBPJ and SKP1, and also interacts with the important factors of Wnt signaling pathways, CTNNB1 and CDH2, regulating tumor proliferation, differentiation, invasion, migration and angiogenesis of PanNENs tumorigenesis." (PMID 33329729, 2020). "To confirm this result, we prepared RNA samples from fresh tumor tissues of 30 CRC patients and a similar result was observed, which demonstrated the positive correlation between SKP1 and CRC-SCs markers." (PMID 33292299, 2020).